FGF21 (fibroblast growth factor 21)
Diseases named in the same sentence as FGF21 in open-access papers (continued):
Sharing a sentence is not in itself a finding about the gene and the disease.
hepatocellular carcinoma (continued). "However, we were unable to detect FGF21 in conditional supernatants from hepatoma cell lines stimulated with pro-inflammatory cytokines (data not shown)." (PMID 23999826, 2013). "Serum FGF21 levels likely reflects the original liver production source and is expected to be a biomarker for functional status of the liver and liver damage leading to hepatoma and disease of liver dysfunction." (PMID 23590285, 2013). "Concordant with previous studies, Fgf21 mRNA expression was upregulated in the HFHFr group, elucidating the protective response of hepatocytes against hepatic inflammation and fibrosis, which may end up in hepatocellular carcinoma." (PMID 34684533, 2021). "Recombinant FGF21 is thought to be a promising treatment option for hepatocellular carcinoma (HCC) and NAFLD." (PMID 31548436, 2019). "The mitokines, fibroblast growth factor 21 (FGF21) and growth differentiation factor 15 (GDF15), are overexpressed during mtUPR activation and are positively correlated with hepatocellular carcinoma progression." (PMID 40943612, 2025). "Adenoviral overexpression of PTP4A1 in human hepatoma cells increased the mRNA levels of FGF21 compared to controls, and shRNA-mediated PTP4A1 knock-down in human hepatoma cells reduced the mRNA levels of FGF21 compared to controls." (PMID 36793871, 2023). "Other treatments that stimulate ERK phosphorylation in hepatoma cells that had been previously shown to upregulate LDL uptake include HGF, FGF21, hGH, PMA and AICAR." (PMID 25811180, 2015). "Having shown bioactivity equivalent to native FGF21 in mouse 3T3-L1 cells, LY2405319 action was next evaluated in HepG2 hepatoma cells that are of human origin and endogenously express Klb and FGFRs." (PMID 23536797, 2013). "Lastly, we show that both during transient regeneration in response to injury and in hepatomas, the expression pattern of the metabolic co-factor KLB is opposite to that of FGF21 in liver." (PMID 23590285, 2013). "The present study observed the effects of β-hydroxybutyrate (β-OHB), the main physiological ketone body, on FGF21 expression in human hepatoma HepG2 cells in vitro and in mice in vivo, and the role of histone deacetylases (HDACs) in β-OHB-regulated FGF21 expression was investigated." (PMID 36045720, 2022). "At the same time, UNC1999 could increase the sensitivity of hepatoma cell lines to sorafenib by down regulating SIRT1, FGF21, FGF21 and VEGFR2." (PMID 34976797, 2021).
chronic kidney disease (32 papers, 2011 to 2025). Impairment of the renal function secondary to chronic kidney damage persisting for three or more months. "An intriguing prospective cohort study in Singapore, involving 1700 Asian people with T2DM and a mean follow-up of 6.3 years, found that in women with T2DM, plasma FGF21 levels independently predicted the risk of progression to end-stage renal disease." (PMID 38312833, 2024). "Other research groups have also reported a close association between FGF21 levels and renal dysfunction and insulin resistance in end-stage renal disease patients." (PMID 24349242, 2013). "Recently we demonstrated a significant and positive association between serum FGF21 and the progression of renal disease, from early- to end-stage chronic kidney disease." (PMID 24349242, 2013). "In addition, the circulating FGF21 level increases progressively from the early to end stages of chronic kidney disease (CKD) and is associated with the renal function." (PMID 28582462, 2017). "However, FGF21 levels have previously been associated with activity of the renin-angiotensin system in patients with end-stage renal disease on dialysis." (PMID 25890271, 2015). "Furthermore, FGF21 was found to closely associated with renal dysfunction in end-stage renal disease subjects." (PMID 21525989, 2011). "Circulating levels of fibroblast growth factor-21 (FGF21) start increasing in patients with chronic kidney disease (CKD) since early stages during the cause of disease progression." (PMID 31848393, 2019). "Regarding the association between FGF21 and diabetic nephropathy, a 6.3-year prospective cohort study in women with T2DM indicated that FGF21 can independently predict the progression to end-stage renal disease." (PMID 36594101, 2023). "Multiple FGFs have been shown to be elevated in patients with chronic kidney disease, including FGF21 and FGF23." (PMID 35215435, 2022). "In this review, we summarize the biological characteristics, regulation and biological function of FGF21 based on the current studies, and briefly discuss the potential relationship with chronic kidney disease." (PMID 34675822, 2021). "Serum FGF21 levels increase with progression of chronic kidney disease (CKD), chronic and acute renal dysfunction, cold-induced thermogenesis, and brown adipose tissue (BAT) activity." (PMID 26594197, 2015). "Serum FGF21 levels correlate with renal function and are markedly increased in chronic kidney disease patients receiving hemodialysis, suggesting a possible link between their FGF21 levels and renal function." (PMID 21331285, 2011). "A meta-analysis involving 28 studies with 19,348 participants indicated that a high serum FGF21 level may predict the incidence of chronic kidney disease (CKD) and renal outcomes in patients with T2DM." (PMID 38312833, 2024). "Based on the results of this current study it may be concluded that the plasma FGF21 concentration in patients with end-stage renal disease is higher than in healthy subjects and significantly decreases after successful kidney transplantation." (PMID 39064306, 2024). "In the context of renal diseases, high FGF21 has recently been revealed as one of the significant markers in various renal dysfunction including the progression of chronic kidney disease (CKD) and the impaired glomerular filtration rate (GFR) and albuminuria in T2DM." (PMID 37009852, 2023). "In the same study, it was determined that serum FGF21 levels decreased by 13% after 6 months of angiotensin receptor blocker treatment in 72 patients with end-stage renal disease, and they stated that these findings suggest a possible connection between RAS and FGF21." (PMID 37374349, 2023). "In addition, it has been indicated that upregulation of serum FGF21 levels may delay the progression of diabetic nephropathy and chronic kidney disease." (PMID 32210821, 2020).
chronic kidney disease (continued). "Finally, this article mentioned that measurement of FGF-21 and FGF-23 was useful for detecting chronic kidney disease (CKD) and its complications, such as cardiovascular disease and metabolic bone disease." (PMID 35574015, 2022). "This study aims to test the hypothesis that elevated FGF21 concentrations are associated with the change of renal function and the presence of left ventricular hypertrophy (LVH) in the different stages of chronic kidney disease (CKD) progression." (PMID 21525989, 2011). "Indeed, end-stage renal disease (ESRD) patients receiving dialysis showed 8- to 15-fold higher circulating FGF21 levels than normal subjects, and circulating FGF-21 levels were inversely correlated with the residual renal function in peritoneal dialysis patients." (PMID 28582462, 2017). "Of 588 subjects screened, 39 patients with end-stage renal disease (ESRD), 17 patients took fenofibrate, and 1 patient without detectable FGF21 value were excluded." (PMID 30127382, 2018).
diabetic cardiomyopathy (30 papers, 2015 to 2025). Diabetic cardiomyopathy is a disorder of the heart muscle in people with diabetes. "FGF21 binds to the heavy and light chains of ferritin, thereby reducing its excessive degradation via the proteasomal and lysosomal autophagic pathways in diabetic cardiomyopathy, causing diabetic cardiomyopathy." (PMID 41198625, 2025). "Recent clinical and subclinical research has demonstrated that increased serum levels of FGF21 are closely linked with diabetic cardiomyopathy, placing it as a potential biomarker for this condition." (PMID 39335666, 2024). "FGF21 ameliorates several metabolic diseases, such as alcoholic fatty liver disease, diabetic cardiomyopathy, and vascular complications associated with AMPK activation." (PMID 31570705, 2019). "FGF21 inhibits age-associated metabolic syndrome and protects against diabetic cardiomyopathy." (PMID 37555575, 2023). "Moreover, FGF21 deficiency exacerbated the development of diabetic cardiomyopathy by aggravating cardiac lipid accumulation." (PMID 30185439, 2018). "In murine models of diabetic cardiomyopathy, high-intensity treadmill running activates an FGF21/AMPK/SIRT3 cascade that phosphorylates FoxO3, stabilizes mitochondria, and limits oxidative injury." (PMID 40861274, 2025). "In mice with diabetic cardiomyopathy, FGF21 protects the heart from inflammation and oxidative stress by activating Nrf2 to increase CD36 expression." (PMID 35369322, 2022). "Studies performed both in vitro and in vivo suggest that FGF21 is a key humoral mediator of the pathological remodeling in diabetic cardiomyopathy." (PMID 35513431, 2022). "Here we consider the potential role of FGF21 in the development of pathological concentric cardiac hypertrophy and diabetic cardiomyopathy." (PMID 35513431, 2022). "FGF21 also prevented myocardial ischemia and diabetic cardiomyopathy via Akt- or AMPK-mediated signaling pathways which regulate lipid and glucose metabolisms." (PMID 27247947, 2016). "Collectively, these data point to FGF21 as a key regulator of cardiac metabolism and a potential therapeutic target for the treatment of diabetic cardiomyopathy." (PMID 26379627, 2015). "The unaddressed question of FGF21’s effect on the development and progression of diabetic cardiomyopathy (DCM) is investigated here with FGF21 knockout (FGF21KO) diabetic mice." (PMID 25823710, 2015). "Therefore, the beneficial involvement of FGF21 in the pathogenesis of diabetic cardiomyopathy is progressively acknowledged." (PMID 39335666, 2024). "There have also been reports that FGF21 could protect against diabetic cardiomyopathy by inhibiting ROS." (PMID 37156793, 2023). "Alternatively, FGF21 neutralizing antibodies might be developed to inhibit FGF21 function in diabetic cardiomyopathy." (PMID 35513431, 2022). "Furthermore, it has been reported that FGF21 prevents diabetic cardiomyopathy via AMPK-mediated antioxidation and lipid-lowering effects in the heart." (PMID 35159376, 2022). "Diabetic cardiomyopathy (DCM) was diagnosed by significant cardiac dysfunction, remodeling, and cardiac lipid accumulation associated with increased apoptosis, inflammation, and oxidative stress, which was aggravated in FGF21-KO mice." (PMID 29445083, 2018). "Furthermore, another study indicated that fibroblast growth factor-21 (FGF21) prevented diabetic cardiomyopathy via AMPK-AKT2-Nrf2 mediated anti-oxidation and lipid-lowering effects in the heart." (PMID 30619098, 2018). "There has been demonstrated that FGF21 could restore the nuclear accumulation of Nrf2 by activating AMPK/AKT pathway and enhance the antioxidant function of cardiomyocytes in diabetic cardiomyopathy mice." (PMID 34773993, 2021). "Moreover, FGF21 deletion in mice exacerbates diabetic cardiomyopathy by aggravating cardiac lipid accumulation, although it is not clear whether this is a direct effect of the lack of FGF21 action on heart or indirect due to altered systemic lipid homeostasis in diabetic FGF21-null mice." (PMID 26379627, 2015).
diabetic cardiomyopathy (continued). "High serum levels of FGF21 are correlated with diabetic cardiomyopathy (DCM); nonetheless, it is not clear whether increased levels contribute to DCM pathogenesis or are involved in repairing injury caused by DCM." (PMID 39597026, 2024). "Our work also revealed that FGF21 deletion-aggravated cardiac lipid accumulation is likely mediated by cardiac Nrf2-driven CD36 upregulation in type 1 diabetic mice, which contributes to increased cardiac oxidative stress and remodeling, and eventual development of diabetic cardiomyopathy." (PMID 27247947, 2016).
sarcopenia (30 papers, 2020 to 2025). Progressive decline in muscle mass due to aging which results in decreased functional capacity of muscles. "The mechanisms underlying FGF-21’s connection to sarcopenia and sleep disturbances are still not well understood." (PMID 41010737, 2025). "In the elderly, elevated serum FGF21 levels were significantly associated with the risk of sarcopenia, low muscle mass, and low grip strength." (PMID 40801027, 2025). "Higher circulating FGF21 levels have already been linked to chronic sarcopenia in older people but its role as a biomarker of acute sarcopenia remains to be explored." (PMID 39458423, 2024). "Notably, recent studies have revealed that FGF21 serum levels are increased in individuals with sarcopenia and are directly correlated with loss of muscle strength." (PMID 40285369, 2025). "Interestingly, although weak, we found a correlation between frailty and uNGAL, a relevant predictor of mortality in patients with cirrhosis, and FGF-21, a biomarker associated with sarcopenia in these patients." (PMID 39595586, 2024). "Additionally, elevated FGF21 and decreased food intake could cause a loss of muscle mass, as sarcopenia in patients with chronic liver disease is an independent factor that contributes to poor prognosis." (PMID 37370867, 2023). "FGF21 is a factor expressed in muscle and liver that plays multiple important roles in combating sarcopenia." (PMID 41140691, 2025). "Regarding the relationship between FGF-21 and sarcopenia, two independent studies indicate higher FGF-21 serum levels among sarcopenic patients than healthy controls." (PMID 41010737, 2025). "This interaction between environmental and genetic factors reveals the potential value of FGF21 in the prevention and treatment of sarcopenia, providing possible avenues for personalized interventions." (PMID 41140691, 2025). "Both included people above 65 years old with primary sarcopenia and both revealed an inverse correlation of the FGF-21 level with handgrip strength." (PMID 41010737, 2025). "The elevated amount of FGF21 in serum can also help diagnose sarcopenia and thus can serve as a novel biomarker that has detrimental effects on the muscle cells." (PMID 37815907, 2024). "This study aims to systemically review the evidence regarding the relationship between FGF-21 levels and Sarcopenia, as well as the related influential factors." (PMID 37386374, 2023). "The goal of this study is to identify and investigate the pathogenesis and pathological process of sarcopenia, as well as the intersection of serum FGF21 levels and the pathological process of sarcopenia." (PMID 37386374, 2023). "The levels of serum FGF21 in sarcopenia and non-sarcopenia were combined and it is easy to find from the results that there was a large heterogeneity between the studies and even conflicting conclusions were drawn." (PMID 37386374, 2023). "Despite the preliminary understanding of FGF21 expression in myocyte effects, we still define sarcopenia by behavioral methods of diagnosis and evaluation, which makes the inclusion criteria of our study more lenient." (PMID 37386374, 2023). "Thus, sarcopenia and sarcopenic obesity may be associated with FGF-21 disorder." (PMID 35250869, 2022). "Muscle-derived FGF-21 plays an important role in aging and obese, and a positive correlation has been found in serum FGF-21 levels and sarcopenia and obese." (PMID 35250869, 2022). "Moreover, serum levels of fibroblast growth factor-21 (FGF-21) are much higher in decompensated cirrhosis patients with sarcopenia." (PMID 40429815, 2025). "In addition, fibroblast growth factor-21 (FGF-21) levels are higher in decompensated cirrhosis patients presenting sarcopenia." (PMID 41373697, 2025). "An important future avenue is better exploring the role of FGF21 in Sarcopenia." (PMID 40285369, 2025).
sarcopenia (continued). "It has been hypothesized that increased FGF21 expression in sarcopenia may promote mitochondrial stress, reduce skeletal muscle glucose uptake, and disrupt skeletal muscle proteostasis." (PMID 40801027, 2025). "Liver-secreted FGF-21 inhibits satellite cells’ function, which leads to sarcopenia." (PMID 41010737, 2025). "However, the meta-analysis from 2023 indicates a lack of strong evidence for the relationship between increased FGF-21 serum levels and sarcopenia." (PMID 41010737, 2025). "FGF21 may thus provide a mechanistic link through MFN‐mediated development of sarcopenia through modulational of MERCs and functional implications of altered glucose metabolism due to mitochondrial structural rearrangement." (PMID 40285369, 2025). "None of these three showed a positive correlation between high FGF-21 serum levels and sarcopenia." (PMID 41010737, 2025). "They examined the correlation between the FGF-21 serum levels and DC-related sarcopenia." (PMID 41010737, 2025). "The study showed significantly elevated serum levels of FGF-21 in DC-related sarcopenia." (PMID 41010737, 2025). "This ambiguity suggests that while FGF21 has protective effects in acute metabolic challenges, its chronic elevation may act as a biomarker of systemic distress and sarcopenia progression." (PMID 41441428, 2025). "FGF21 may have a muscle catabolic function; elevated serum levels of FGF21 affect muscle strength and mass, and correlate with the development of sarcopenia." (PMID 37962457, 2023). "In addition, it has been concluded that serum FGF-21 levels have a positive correlation with primary sarcopenia." (PMID 37386374, 2023). "The apparent contradiction between the elevated circulating FGF21 in obese patients in a previous study and the finding of sarcopenia in the present study may be an interesting mechanistic link between chronic metabolic conditions and muscle loss." (PMID 37386374, 2023). "Up until now, the metabolism-related pathways by which FGF21 affects skeletal muscle mass are still in the hypothetical conjecture stage, but most investigators believe that serum FGF21 levels have a positive correlation with aging sarcopenia." (PMID 37386374, 2023). "Systemic levels of cytokines such as Tumor Necrosis Factor-α (TNF-α) and other hepatokines such as Fibroblast growth factor 21 (FGF21) may modulate sarcopenia and muscle function respectively as well." (PMID 34040583, 2021). "However, FGF21 may play a passive role, being secreted in response to muscle damage or sarcopenia in an effort to restore balance." (PMID 39764565, 2025). "Notably, this finding is suggestive that exercise mitigates age‐related muscle atrophy, with implications for potential FGF21‐dependent pathways, which may involve mitochondrial dynamic alterations in aging and sarcopenia." (PMID 40285369, 2025). "In addition, FGF21 levels were found to be associated with an increased likelihood of sarcopenia, low muscle mass, and low muscle strength, independent of sex, age, and BMI." (PMID 40171198, 2025). "The animal-based studies and several substudies of clinical trials on sarcopenia that we have reviewed so far have found that muscle-dependent elevations of FGF21 may be associated with muscle aging, myocyte atrophy, and FGF 21 was once proposed as a specific serum candidate marker for sarcopenia." (PMID 37386374, 2023). "In OP and sarcopenia, endocrine-derived FGFs (FGF19, FGF21, and FGF23) modulate bone mineral synthesis and decomposition as well as muscle tissues." (PMID 38902808, 2024). "However, our combined statistics of published studies showed that the correlation between FGF21 and sarcopenia was diametrically opposed in different studies and that this correlation existed at a weak level, regardless of whether the relationship was positive or negative." (PMID 37386374, 2023).